CXCR3 (C-X-C motif chemokine receptor 3)
Diseases named in the same sentence as CXCR3 in open-access papers (continued):
Sharing a sentence is not in itself a finding about the gene and the disease.
autoimmune thyroiditis (8 papers, 2014 to 2024). "CXCL10 plays a central role in thyroid autoimmune diseases, being involved, in the amplification of the Th-1-oriented immune response and ultimately in the recruitment of infiltrating lymphocytes expressing its receptor CXCR3." (PMID 34224085, 2021). "In the autoimmune thyroiditis (AIT), DHA inhibits the CXCR3/PI3K/AKT/NF-κB signaling pathway which executes important roles in AIT." (PMID 33658929, 2020).
cervical cancer (8 papers, 2021 to 2025). A primary or metastatic malignant neoplasm involving the cervix. "On the other hand, high SULTIEI, RAB3C, CXCR3, PROX2, and KRT42P expression was associated with a better prognosis in cervical cancer." (PMID 37350944, 2023). "High expression of MYH1, MYH4, FGG, DEPP1, and ZBTB16 was associated with shorter overall survival of patients with cervical cancer; high expression of SULT1E1, RAB3C, CXCR3, and PROX2 was associated with longer overall survival of patients with cervical cancer." (PMID 37350944, 2023). "The results showed that high expression of MYH1, MYH4, FGG, and DEPP1 was associated with shorter overall survival of patients with cervical cancer; high expression of SULT1E1, RAB3C, CXCR3, and PROX2 was associated with longer overall survival of patients with cervical cancer." (PMID 37350944, 2023). "Therefore, more studies are needed to determine the precision of combining CXCR3 expression, tumor-infiltrating T-cell isoforms, and anti-PD-1/PD-L1 treatment response in patients with cervical cancer." (PMID 35847936, 2022). "Moreover, it has been also demonstrated that CXCL10 and its receptor CXCR3 were expressed by cervical cancer cells." (PMID 36207693, 2022). "This may explain why CXCR3 expression is higher in cervical cancer, but it may also indicate a better prognosis for patients with cervical cancer." (PMID 35847936, 2022). "The results suggested that CXCL9/10/11 in the tumor microenvironment may recruit CD8+ T cells and NK cells through the CXCL9–11/CXCR3 axis, thereby improving the survival of cervical cancer patients by inhibiting the development and progression of tumors." (PMID 34321012, 2021). "In cervical cancer research, ESTIMATE has been used to analyze gene expression data from cervical cancer tissues and to investigate the association between the tumor microenvironment and patient outcomes, CXCR3 axis may be a new therapeutic target for cervical cancer." (PMID 37594950, 2023). "Chen and colleagues have demonstrated, in other HPV-driven cancers, specifically HPV-positive cervical cancer, that CXCL10 is upregulated and its receptor CXCR3 is overexpressed." (PMID 37686653, 2023). "For example, CXCR3 was found to be an important factor in CD8+ T cell recruitment and tumor immunological infiltration in cervical cancer." (PMID 35847936, 2022). "The HPV-positive (HPV+) cervical cancer cell lines SiHa and Caski secreted increased levels of CXCL10 compared to human foreskin fibroblasts (HFF-1), and its receptor CXCR3 was overexpressed in HFF-1." (PMID 34422627, 2021). "The results indicate that HPV infection can induce cervical cancer cells to secrete CXCL10, which binds to CXCR3 in the surrounding fibroblast cells,leading to JAK-STAT pathway activation and the subsequent upregulated expression of exosomal PD-L1." (PMID 34422627, 2021). "We can infer that CXCL10/CXCR3 axis and PD-1+CXCL10+ T cells may also play specific roles corresponding to their distribution in cervical cancer." (PMID 35847936, 2022).
co-infection (8 papers, 2011 to 2024). "The molecular mechanisms underlying the accelerated up-regulation of intrahepatic CXCR3-associated chemokines in HCV/HIV-1 coinfection are associated with HIV-1-related microbial translocation, viral protein stimulation, and antiviral immune responses." (PMID 24516541, 2014). "Compared to HCV infection, HCV/HIV-1 coinfection further increased intrahepatic mRNA expression of all three CXCR3-associated chemokines." (PMID 24516541, 2014). "Interestingly, CXCR3 expression increased in HIV-HCV co-infection vis-à-vis in HIV and HCV mono-infections - probably caused by an additional infection." (PMID 27091211, 2016). "Together, these results show that CXCR3 and not CCR5, is functionally important for CD4+ T-cell migration during CHIKV infection, and co-infection sufficiently abrogates CXCR3-mediated joint swelling." (PMID 30254309, 2018). "Our data demonstrate that intrahepatic CXCR3-associated chemokines are the most markedly elevated in HCV infection, and are further elevated in HCV/HIV-1 coinfection." (PMID 24516541, 2014). "We thus hypothesized that during CHIKV‐PbA co‐infection, higher levels of CXCR3‐cognate chemokines may be induced in the spleen to mediate splenic retention of CD8+ T cells and internalization of surface CXCR3." (PMID 29113976, 2018). "Finally, expression of CXCR3 on CD56bright NK cells was increased in HIV-HCV co-infection in comparison to HIV mono-infection while remaining similar to HCV mono-infection." (PMID 27091211, 2016). "In addition, our study showed an elevated expression of CXCR3 on CD56bright NK cells in HIV-HCV co-infection as compared to HIV and HCV mono-infected groups which may reflect an effort to recruit more CD56bright NK cells to liver in the wake of a co-infection." (PMID 27091211, 2016). "Thus, HIV-HCV co-infection is able to modulate the phenotype of CD56bright NK cell subset in a unique way such that NKp46 and CXCR3 expressions are distinct for co-infection while both mono-infections have an additive effect on CD56bright, CD69 with CD95 expressions." (PMID 27091211, 2016). "This occurs through the induction of higher splenic IFNγ during co‐infection, leading to higher local levels of CXCL9 and CXCL10 that retains the CXCR3‐expressing CD8+ T cells in the spleen." (PMID 29113976, 2018). "During co‐infection, CD8+ T cells had lower CXCR3 levels in the spleen, with the difference being especially stark in Pb1‐specific CD8+ T cells." (PMID 29113976, 2018). "Compared with HCV infection, HCV/HIV-1 coinfection did not dramatically affect intrahepatic gene expression profiles of cytokines and their receptors, but profoundly altered expression of several chemokine genes including up-regulation of the CXCR3-associated chemokines." (PMID 24516541, 2014). "Expression of CXCR3 in co-infection is clearly different as it is not reduced as much as in either mono-infections so this combination is also unique for HIV-HCV co-infection." (PMID 27091211, 2016).
glomerulonephritis (8 papers, 2013 to 2025). A renal disorder characterized by damage in the glomeruli. "In fact, the cytokine was assumed to attenuate CXCL10/CXCR3‐dependent infiltration of T lymphocytes during glomerulonephritis." (PMID 41287825, 2025). "As such, we assessed anti-ETAR and anti-CXCR3 antibody levels in patients with specific forms of glomerulonephritis and compared them with those of healthy controls." (PMID 39768675, 2024). "In human glomerulonephritis, CXCR3 is mainly expressed in the interstitial infiltrating T cells, and their number correlates with renal function, proteinuria, and percentage of globally sclerosed glomeruli." (PMID 36686486, 2022). "The chemokine receptor, CXCR3, is expressed on T cells and contributes to T cell recruitment in murine glomerulonephritis." (PMID 33676416, 2021). "Furthermore, anti-ETAR and anti-CXCR3 antibodies are found in healthy individuals, increasing the likelihood that they are active in glomerulonephritis patients and that the evaluation would produce crucial results." (PMID 39768675, 2024). "Furthermore, CXCR3+ Tregs are potentially important for ameliorating glomerulonephritis during ANCA vasculitis." (PMID 36381498, 2022). "Interestingly, deletion of CXCR3+ in Tregs leads to aggravated glomerulonephritis in a murine model of nephrotoxic glomerulonephritis." (PMID 36381498, 2022). "Therapeutically targeting CXCL10 or CXCR3 may therefore reduce the inflammatory response in glomerulonephritis and may possibly affect the PD-1 axis." (PMID 33676416, 2021). "Th1 and Th17 cells reportedly mediate glomerulonephritis in MRL/lpr mice, and a deficiency in the chemokine receptor CXCR3 significantly improves morphology and function of nephritic kidneys via interference with the trafficking of both Th1 and Th17 cells into the inflamed kidneys." (PMID 31930150, 2019).
liver cancer (8 papers, 2016 to 2025). An epithelial or non-epithelial malignant neoplasm that arises from the liver. "It has been suggested that CXCR3 is assigned to the migration of liver cancer cells." (PMID 29734668, 2018).
lymph node metastasis (8 papers, 2009 to 2025). "The expression level of CXCR3 was significantly correlated with clinicopathological factors such as tumor differentiation, lymph node metastasis, distant metastasis, and Dukes’ stage." (PMID 36479091, 2022). "The high levels of CXCR3 expression led to increased lymph node metastasis and worsened outcomes in patients, when compared to non-CXCR3 expressors." (PMID 35203305, 2022). "Patients with CXCR3-positive tumors were significantly more likely to develop lymph node metastasis." (PMID 36479091, 2022). "Third, CXCL10 is an independent predictor of lymph node metastasis of the primary tumor, and co-expression of CXCL10/CXCR3 was associated with postoperative recurrence." (PMID 33195424, 2020). "Survival analysis was performed to assess the value of CXCL10 as an independent predictor of the existence of lymph node metastases with its corresponding receptor CXCR3." (PMID 33195424, 2020). "In clinical lung adenocarcinoma tissue samples, both CCR7 and CXCR3 were expressed, with CXCR3 having a higher frequency, 90% vs. 65%; however, only CCR7 was associated with lymph node metastasis and not CXCR3 in these human tissues." (PMID 35203305, 2022). "Other cell adhesion molecular markers associated with lymph node metastasis, such as the chemokine receptors CCR7, CXCR3 and CCL21, could be related to distant metastasis development." (PMID 28705152, 2017). "Other cell-adhesion-molecular markers associated to lymph-node metastasis, as chemokine receptors CCR7, CXCR3 and CCL21, could be related to brain metastasis development, thus, studies about analysis of their association with brain metastasis development are justified." (PMID 19386089, 2009). "The expression of CXCR3 was correlated to gender (P = 0.025), especially to women patients, but not correlated to age, Lauren classification, TNM stage and lymph node metastasis." (PMID 29690901, 2018).
metastatic disease (8 papers, 2017 to 2025). "The expression of CXCR3 increased, however, with malignant transformation and achieved its highest expression in metastatic tumors." (PMID 32225066, 2020). "The CXCR3/CXCL10 axis seems to be involved in metastatic disease in several tumour types." (PMID 39146303, 2024). "Interestingly, metastatic tumors exhibit increased expression of CXCR3, CCR2, IL-4, IL-12p40, and IL-17." (PMID 32225066, 2020). "Changes in CXCR3 profile expression may be related to initial stages of cancer development or its progression to metastatic disease." (PMID 29416784, 2018).
parasite infection (8 papers, 2019 to 2024). "This hypothesis is corroborated by former observations that correlate higher expression of some X-linked genes (Tlr7, Cxcr3, and Tlr8) in females compared to males with better protection against viral or parasite infections in both humans and mice." (PMID 38701219, 2024). "In addition, all anti-CXCR3 treated mice which presented high parasitemia became susceptible and died very quickly due to infection when compared to controls, which had a 100% survival rate." (PMID 32574175, 2020). "In parasitic infection including some important members of apicomplexan parasites, the expression of CXCR3 was highly up-regulated on CD4+ and CD8+ T cells in the spleen during Plasmodium berghei-mediated cerebral malaria." (PMID 36704563, 2022). "After the peak, parasitemia in isotype control and anti-CXCR3 treated groups decreased, and on day 13, the parasitemia levels increased again only in anti-CXCR3 treated group." (PMID 32574175, 2020). "The parasitemia level in the anti-CXCR3 group remained high until day 15 after infection in contrast with the Isotype control group." (PMID 32574175, 2020). "For that propose, C57BL/6 mice were infected with T. cruzi and treated with anti-CXCR3 antibody every 48 hours, first, we evaluated the parasitemia and survival rate, also, we investigated the function, activation and migration of specific CD8+ T cells." (PMID 32574175, 2020). "Our results show the increase in parasitemia and precocious mortality in anti-CXCR3-treated T. cruzi-infected mice." (PMID 32574175, 2020). "Parasitemia peaked on day 10 p.i. in both genotypes, but the percentage of pRBC was significantly higher in infected CXCR3−/− compared to WT mice." (PMID 30915078, 2019). "Parasitemia levels were significantly higher around the time of peak parasitemia in CXCR3−/− compared to WT mice but survival was similar suggesting a role for CXCR3 in controlling parasite replication during acute P. chabaudi AS infection." (PMID 30915078, 2019). "CXCR3−/− mice had significantly higher parasitemia levels around the time of peak parasitemia than WT mice." (PMID 30915078, 2019). "They recruit circulating T cells to the skin in a CXCR3-dependent manner and control the parasite infection, and this allows us to draw the conclusion that optimal protective immunity to this parasite and effective vaccination depends on generating both circulating and skin-resident memory T cells." (PMID 39201440, 2024). "Parasitemia increased to similar levels through day 8 p.i. in infected WT and CXCR3−/− mice." (PMID 30915078, 2019). "Moreover, after anti-CXCR3 treatment, all mice had an increased parasitemia and burden of tissue parasitism, and died due to infection, showing that CXCR3, but not CCR2, had a pivotal role in T. cruzi resistance." (PMID 31356587, 2019). "Taken together, CXCR3 and its ligands promote T cell trafficking in cell-mediated immunity, making it reasonable to believe that these chemokines may have a vital role in the pathogenesis of parasitic infections in the CNS." (PMID 36704563, 2022). "CXCR3 is required for memory CD8+ T cell recruitment to the lung during Mycobacterium tuberculosis infection and during intracellular parasitic infections." (PMID 38709823, 2024). "The work focussed on an intestinal intracellular parasite infection, Eimeria vermiformis, invoking a type-1 dominated response with CD8+ TRM cell development dependent on type-1, Tbet- and CXCR3-expressing, TREG cells." (PMID 37696824, 2023). "It should be noted that the increases in CD4+CXCR3+ T cells and CD4+IFN-γ+ T cells observed in the spleen of infected WT mice were coincident with high parasitemia levels in infected CXCR3−/− mice." (PMID 30915078, 2019).
parasite infection (continued). "After anti-CXCR3 administration into ASP2-vaccinated and challenged mice, we observed a trend in parasitemia increase only on day 12 after infection, when the peak of parasitemia was noticed, when compared to the immunized and isotype-treated control group (ASP2+T." (PMID 31356587, 2019).
Sjogren syndrome (8 papers, 2019 to 2024). An autoimmune disorder in which immune cells attack and destroy the glands that produce tears and saliva. "The only known simultaneous assessment of anti-ETAR and anti-CXCR3 antibodies is described in patients with Sjogren syndrome." (PMID 39768675, 2024). "CXCR3 antibodies impact Sjogren syndrome development, with lower anti-CXCR3 autoantibody levels being found in Sjogren syndrome patients than in healthy individuals." (PMID 39768675, 2024). "This study aimed to investigate the serum and expression levels of C-X-C motif chemokine ligand 9 (CXCL9), CXCL10, CXCL11, and CXC receptor 3 (CXCR3) in minor salivary glands (MSGs) of patients with primary Sjögren’s syndrome (pSS), and to explore their correlations with clinical parameters." (PMID 38900301, 2024). "Although CXCR3 is expressed in all innate immune cells, CXCR3+CD163+ M2-like macrophages may contribute to anti-inflammatory functions in primary Sjögren’s syndrome lesions." (PMID 35562903, 2022). "The other examples are CCL2, IL7, CXCR3, and CXCL12, which are found in scleritis, dry eye disease, glaucoma, dry eye disease, and Sjögren’s syndrome." (PMID 31810226, 2019). "Notably, and in contrast to previous studies of SLE ASC52, and of Sjogren’s syndrome ASC60, SLE ASC exhibit distinctive characteristics, including high levels of the chemokine receptors CXCR4 and CXCR3, largely in combination." (PMID 38429276, 2024).
ZIKV infection (8 papers, 2018 to 2023). "In fact, previous research has implicated CXCR3+TFH in HCV infection, Zika virus infection, and acute febrile malaria and vaccination in children." (PMID 35619703, 2022). "Our findings of reduced activation, reduced CXCR3 expression and reduced cytotoxicity of decidual memory T lymphocytes in ZIKV infection indicate local immunosuppression and impaired immune recruitment as possible mechanisms of vertical transmission." (PMID 34394129, 2021). "Overall, we have demonstrated an anti-viral role for IP-10/CXCR3 signaling during ZIKV infection of human prostate cells and that anti-viral activity is dampened by passaging virus through multiple cell types." (PMID 33378361, 2020). "Future studies also need to address the mechanism of IP-10/CXCR3 anti-viral responses in ZIKV infections of human testicular and epididymal cells." (PMID 33378361, 2020). "While both CXCR3 isoforms are upregulated during ZIKV infection, CXCR3-A is significantly more abundant on prostate epithelial cells during early infection with ZIKV-FLA or FLR propagated in one cell type (referred to as FLA/1 and FLR/1)." (PMID 33378361, 2020). "If IP-10/CXCR3 restricts ZIKV infection in other urogenital tract tissues and the mechanism of action is identified, IP-10/CXCR3 signaling could serve as a potential therapeutic target to ultimately interrupt sexually-transmitted ZIKV infections." (PMID 33378361, 2020). "To determine if CXCR3 anti-ZIKV activity is a result of altered cellular viability during infection, we performed similar studies with pre-treatment of IP-10 and ZIKV infection in prostate cells." (PMID 33378361, 2020). "While these limitations dampen the overall interpretation of IP-10/CXCR3 effects on ZIKV replication, it is an important starting point for investigating IP-10/CXCR3 effects during ZIKV infection." (PMID 33378361, 2020). "DENV and ZIKV infections and DENV/ZIKV coinfections similarly induced expression of CCR5, CX3CR1, and CXCR3 on CD4 and CD8 T cells." (PMID 29282904, 2018). "Even without specific in vitro antigenic stimulation, DENV, ZIKV, and DENV/ZIKV infections induced expression of CCR5, CX3CR1, and CXCR3 on CD4+ and CD8+ T cells, indicating an activated status of these cells." (PMID 29282904, 2018). "As expected, IFN-γ+ Tfh cells expressed higher levels of T-bet, Eomes and CXCR3 than IFN-γ− conventional Tfh cells, but lower than Th1 cells; and T-bet was slightly downregulated in IFN-γ+ Tfh cells on day 14 compared with that on day 7 after ZIKV infection." (PMID 31455769, 2019). "However, the mechanisms of action for CXCR3 in ZIKV infection have not been elucidated, and here we report the first studies indicating its anti-viral role." (PMID 33378361, 2020). "Absence of CXCL10, which is one of the ligands for CXCR3, did not affect protection levels implying that other CXCR3 ligands might be more critical for the recruitment of CD8 T cells in the context of ZIKV infection." (PMID 32973802, 2020).